S100A9 (S100 calcium binding protein A9)
Diseases named in the same sentence as S100A9 in open-access papers (continued):
Sharing a sentence is not in itself a finding about the gene and the disease.
tumor (continued). "However, in animal models of breast cancer with brain metastases, CD11b-positive myeloid cells have been found to aggregate and form the “soil” for early tumor metastasis; this further releases the inflammatory factors S100A8 and S100A9, inducing tumor cell chemotaxis." (PMID 36338717, 2022). "Therefore, we hypothesized that elevated S100A9 levels in BRCA1-MT mammary epithelial tissue might progressively direct immunosuppressive milieu formation and promote tumor initiation and progression in mammary tissues." (PMID 35304461, 2022). "Similarly, the degree of mRNA expression of S100A9 was a negative prognostic marker, and it has been correlated with tumor differentiation and development in NSCLC patients." (PMID 33567747, 2021). "Moreover, the number of tumor-infiltrating M2-like Mφ was more in Fn-positive CRC tissues accompanied by higher S100A9 expression than that in Fn-negative tissues with lower S100A9 expression." (PMID 34093546, 2021). "At the same time, IFN-γ activates myeloid-derived suppressor cells (MDSC), which might lead to the observed elevated S100A9 expression since S100A9 is not released during therapy-induced lysis of the tumor cells." (PMID 33401528, 2021). "During cellular stress, S100A8 and S100A9 is released as a heterodimer (e.g., calprotectin) into the extracellular space where it binds to TLR4 and initiate a signaling cascade that regulates inflammation, cell proliferation, differentiation, and tumor development in an NF-κB-dependent manner." (PMID 33679877, 2021). "We also evaluated the combined influence of S100A9+ cells in tumor and nontumor regions." (PMID 34157683, 2021). "Mice lacking S100A9 mounted potent anti-tumor immune responses due to lack of MDSC induction." (PMID 34572138, 2021). "Moreover, miR-196a promoted tumor progression by down-regulation of SPRR2C, S100A9 and KRT5." (PMID 33289788, 2021). "The S100A9-specific in vivo imaging presented here allows the assessment of changes in the natural TME non-invasively and longitudinally over time, reflecting immediate and divergent therapy effects, even before the size or morphology of the tumor are responding." (PMID 33401528, 2021). "We found that neutrophils predominantly infiltrated the nontumoral area rather than the tumoral area, and CD15+ cells were the main cell population that expressed S100A9 protein (58.19 ± 20.80%) in nontumor areas, but this proportion was significantly reduced in tumor areas (29.01 ± 24.20%)." (PMID 34157683, 2021). "Furthermore, previous studies have revealed that tumor-infiltrating monocytes and macrophages could promote tumor invasion and migration by upregulating S100A8 and S100A9 expression in cancer cells." (PMID 33193702, 2020). "To test whether the S100A9 and TNC serum levels are influenced by other factors, we analyzed correlations between the serum biomarker concentrations and the demographic information, clinical features and tumor characteristics in CRC patients." (PMID 31632476, 2019). "Likewise, our analysis revealed an upregulation of genes S100A8 and S100A9 which have previously been reported as salivary biomarkers of OSCC, whose expression has been shown to induce tumor-infiltrating monocytes and macrophages leading to increased cancer cell invasion and metastasis." (PMID 30018735, 2018). "After intravasation, most of tumor cells in circulation are damaged by the shear stress and mechanical stresses in blood, thus releasing intracellular molecules, many of which have been identified as the ligands for TLR2/4, including HMGB1, HSP60, HSP70, gp96, S100A8, S100A9, SAA3 and so on." (PMID 28415700, 2017). "Since the gMDSCs derived from metastatic 4T1 tumour-bearing animals were able to suppress the EMT-related genes and also induce distinct set of genes; S100A9, MMP8, S100A8, WFDC21, LYZ2, FPR1, CCL3, TGFb2, we reasoned whether these genes could be specific for metastatic/aggressive behaviour." (PMID 28382931, 2017).
tumor (continued). "On the other hand, before tumor arrival in the metastatic sites, the primary tumor also produces systemic factors, for example, VEGFA, TGFβ, TNF, and LOX, which induce chemotactic protein expressions like S100A8, S100A9, SAA3 and extracellular matrix remodeling." (PMID 29450136, 2017). "Interestingly, S100A8 and S100A9 dysregulation was similar across all tumor grades (T) and was independent of nodal involvement (N) or distant metastasis (M)." (PMID 26883112, 2016). "Heterocomplex of S100A8/S100A9 can influence migration of MDSC and may induce tumour cell invasion." (PMID 26880885, 2016). "We found ~10-fold more tumor necrosis factor-α (TNFα) in tumor-infiltrating monocyte/macrophage-conditioned media compared with the conditioned media from naive monocytes/macrophages, suggesting TNFα as a possible candidate for the induction of S100A8 and S100A9." (PMID 27086923, 2016). "We also found an enhanced recruitment of inflammatory cells, including S100A9+ neutrophils, to the colons of Ripk3−/− mice after AOM-DSS, which is in line with the role of these cells in up-regulating the Wnt-β-catenin pathway in tumor cells and CRC progression." (PMID 27344176, 2016). "Expression of S100A9 was restricted to the prickle and functional layers of normal esophageal mucosa and localized predominantly in the cytoplasm and nucleus whereas virtually no expression was observed in the tumor and stromal cells." (PMID 26788548, 2015). "However we still cannot completely deny a possibility that the drop in S100A9 is just a consequence of tissue destruction/tumor progression and can decrease irrespective of CHI3L1." (PMID 26431492, 2015). "We concluded from these data that the absence of S100A9 expression delays TRAMP tumor growth." (PMID 22470535, 2012). "Interestingly, mice lacking S100A9 showed significantly reduced tumor incidence, growth and metastasis, reduced chemokine levels, and reduced infiltration of CD11b+ Gr1+ cells within tumors and pre-metastatic organs." (PMID 23166536, 2012). "Since RAGE has been shown to be important in tumor growth in other systems, it is not far fetched to suggest that the effect of the S100A9/RAGE interaction might be different than the S100A9/TLR4 interaction in the regulation of tumor growth." (PMID 22470535, 2012). "Similar results were obtained by Ichikawa and co-authors on colon tumors, where in mice lacking S100A9 the authors observed significantly reduced tumor incidence, growth and metastasis, decreased chemokine levels and declined infiltration of CD11b+ Gr1+ cells within tumors and premetastatic organs." (PMID 22489132, 2012). "In tumor‐bearing mice, both tasquinimod treatment and CD300ld gene knockout inhibited PMN‐MDSC migration and reduced immunosuppressive effects, suggesting that drugs targeting CD300ld could exhibit comparable antitumor efficacy to those targeting S100A8/S100A9." (PMID 40452814, 2025). "Moreover, S100A9 released into the TME by monocytes and myeloid-derived suppressor cells can affect the carbohydrate and lipid metabolism and induce abnormal oxidative metabolism by the activation of NADPH oxidase of both tumor cells and their surrounding cells." (PMID 39195201, 2024). "Furthermore, by using S100A9 knockout transgenic mice, which have an impaired MDSC response to cancer, it has been observed a significant delay in tumor growth, which was reverted by adoptive administration of MDSCs, thus evidencing the key role played by MDSCs in tumor escape from immune system." (PMID 25538892, 2014). "Thus, both S100A9 and its receptor TLR4 may be involved in tumor development." (PMID 22470535, 2012). "Specific members such as S100C, S100A8, S100A9, and S100A13 exhibit distinct expression patterns in non-muscle-invasive and muscle-invasive disease, with functional implications for tumor behavior." (PMID 41404073, 2025).
tumor (continued). "Among the genes upregulated in the tumor compartment (79 PanCK+ segments from 10 patients) of non-responders, the most differentially expressed were IDO1, HLA-F, S100A8, and S100A9." (PMID 37835599, 2023). "There was a remarkable and significant increase of positive IRS regarding the tumor center compared to the invasion front for both HPV+ (p = 0.0093) and HPV− (p = 0.0013) PeCa for the Calprotectin subunit S100A9 but not for S100A8." (PMID 36303837, 2022). "It was previously shown that, in the absence of S100A9, the MDSC population is reduced, resulting in reduced tumor size in tumor-bearing mice, while its overexpression leads to an accumulation of MDSCs and impaired DC differentiation." (PMID 33465053, 2021). "Notably, ABR-238901, a small molecule that inhibits the interaction of S100A9 with its receptors, decreases the secretion of IL-6 and IL-10 from MDSCs, inhibits the neoangiogenic process, but would not have shown satisfactory efficacy in reducing tumour progression." (PMID 34445745, 2021). "Partially expressed also in the tumor, potential negative tumor markers with a MW of 4615 Da and 15126 Da had little added value to S100A8 and S100A9." (PMID 32733643, 2020). "In particular, we noted that S100A8 and S100A9 transcript levels in GBM have a significant, positive, high correlation with stromal scores and a significant, negative, correlation with tumor purity score." (PMID 30808902, 2019). "We had previously shown that myeloid cells suppressed ANGPTL7 expression in cancer cells, leading to decreased tumor cell proliferation, and in keeping with this, S100A8 or S100A9 knockdown did not alter ANGPTL7 mRNA levels." (PMID 27086923, 2016). "Despite lacking a concordant relation of S100A9 and CD68 expression (data not shown), the increase of S100A9 or CD68 in tumor stroma significantly reduced patient recurrence-free survival (Left, p = 0.012)." (PMID 26315114, 2015). "We conclude from these results that S100A9 production is induced in TRAMP tumors, and that the most likely primary source of the protein are CD11b+ cells and not tumor cells." (PMID 22470535, 2012). "As EL4 tumor growth was not reduced in RAGE−/− mice, we concluded that the interaction of S100A9 with TLR4 promotes tumor growth." (PMID 23234398, 2012). "Therefore, S100A9 may be involved in initial tumor formation rather than in metastasis." (PMID 23166536, 2012). "Comparing S100A9 expression in 70 HCC with non-carcinomatous hepatocytes and bile duct epithelia revealed exclusive immunoreactivity in tumor cells." (PMID 23166536, 2012). "However, the role of S100A9 in regulating SCLC growth and metastasis and its downstream effects in modulating the functions of tumor and immune cells in TME have not been studied." (PMID 41173834, 2025). "Immunostaining was also used to validate microarray analysis and found increased expression of S100A9 and REG1α in CA-CRC and in non-dysplastic tissue from patients with UC harbouring remote neoplasia, compared to patients with UC and without neoplasia and controls." (PMID 34200768, 2021). "Additionally, tumor growth in a mouse model was significantly reduced in the absence of S100A8 and S100A9, respectively, thereby emphasizing the impact and pathophysiological relevance of our findings." (PMID 32503348, 2020). "But, tumor cells with transient decrease of Smad4 do not react to S100A8, but not S100A9." (PMID 33117687, 2020). "The analysis of TCGA transcript levels of high abundant proteins found in our study revealed that a good fraction of them, including S100A8 and S100A9, showed higher transcripts in GBM and significant positive correlation with stromal scores and negative correlation with tumor purity score." (PMID 30808902, 2019). "S100A9-specific SPECT imaging showed a higher tracer uptake in lungs, spleen and tumor of mice, implanted with metastatic 4T1.2, as compared to non-metastatic 67NR and non-tumor-bearing control mice." (PMID 28744322, 2017).
tumor (continued). "All together, these findings pointed out that S100A9, rather than S100A8/S100A9, could be the main mediator of inflammatory diseases and tumours and, more importantly, is emerging as a potential target for the treatment of malignant diseases." (PMID 23626736, 2013). "Furthermore, over-expression of S100A9 or S100A8/A9, but interestingly not S100A8, promoted tumor growth and MDSC development in parallel." (PMID 22470535, 2012). "Notably, the peptide fragment of S100A9, detected in GBM saliva but not in CTRL, could confirm the outlined role of S100A9 in tumor progression and aggressiveness." (PMID 41155285, 2025). "However, in vitro stimulation of human-derived macrophages with S100A8/S100A9 purified proteins failed to induce cytokine production, possibly due to required interaction of the S100A8/S100A9 heterodimer with additional factors from the tumor microenvironment." (PMID 35440136, 2022). "As S100A9 tetramers do not induce higher activation of NK cells towards K562 target cells, whereas they increase anti-HIV-1 activity, it is tempting to speculate that the signalling they induce in NK cells prompts the cells to better respond to an HIV-1 infected cell compared to a tumor cell line." (PMID 24156302, 2013).
cancer (309 papers, 2005 to 2026). A tumor composed of atypical neoplastic, often pleomorphic cells that invade other tissues. "Calprotectin, a heterodimer of the S100A8 and S100A9 proteins, has been implicated in cancer-related inflammation and metastasis." (PMID 40869349, 2025). "S100A9 is an important immune-related protein associated with inflammation or cancer, and is believed to promote the occurrence, development, and metastasis of tumors." (PMID 39882072, 2024). "In CRC mouse models, TAN-derived extracellular vesicles also promote cancer progression, partly by increasing cancer stemness, whereas S100A9-deficient extracellular vesicles lack this effect." (PMID 39795864, 2024). "Calprotectin, a heterodimer formed from the combination of S100A8 and S100A9 proteins, is commonly upregulated in many tumors and likely plays a critical (essential) role in inflammation-associated cancers." (PMID 39201484, 2024). "S100A9 has been reported to regulate the behavior of cancer cells by inducing pre-metastatic cascades associated with cancer spread." (PMID 39175079, 2024). "The S100A8 and S100A9 genes are located on chromosome 1q21, and the deletion or mutation of these chromosomes is associated with the occurrence of cancer." (PMID 36768433, 2023). "elegantly showed in their in vitro experiments that under the influence of PSC, cancer cells increased the secretion of S100A9, causing the increased expression of PD-L1 on monocytes/macrophages." (PMID 37519820, 2023). "Retrieving the immune-TME and TNBC aggression-associated marker genes from the Pan-cancer TCGA-dataset, we found a high positive correlation of the expression of S100A9 and S100A8, two immune suppression marker genes, with AURKA and EZH2 in the TNBC samples." (PMID 37189841, 2023). "S100A9 have been reported to be as Damage-associated molecular patterns (DAMPs) and involved in almost all aspects of cancer biology, such as proliferation, tumorigenesis, apoptosis, invasion, metastasis and angiogenesis." (PMID 34689294, 2021). "Upregulation of S100A9, on the other hand, seems associated with tumor progression and metastasis in most cancer forms." (PMID 34067757, 2021). "S100A9 has emerged as an effective pro-inflammatory mediator in acute and chronic inflammation, and can play a critical role in cancer associated with inflammation." (PMID 33806004, 2021). "High monocyte count and S100A9 levels were also associated with short cancer-specific survival, with monocyte count providing independent prognostic information." (PMID 34067757, 2021). "S100A9 is differentially expressed in various cell types and is associated with the development, progression and metastasis of various cancers." (PMID 34157683, 2021). "For secreted proteins from culture medium, soluble proteins such as s100A8 and s100A9, which have been shown to be associated with cancer cell invasion, were only detected in highly metastatic 5-8F cells, but not lowly-metastatic 6-10B cells." (PMID 33020562, 2020). "Among these genes, S100A8 and S100A9 have been identified as novel diagnostic markers of human cancer." (PMID 31480483, 2019). "S100A8/S100A9 expression in epithelial cancer cells causes enhanced infiltration of immune cells, especially neutrophils, and stimulates settlement of the cancer cells in the lung." (PMID 31208368, 2019). "Several genes downregulated or upregulated by S100A9 knockdown were associated with proliferative properties or apoptosis or invasion of cancer cells." (PMID 31055998, 2019). "S100A8/S100A9 proteins regulate the behaviour of cancer cells by inducing pre-metastatic cascades associated with cancer spread." (PMID 30558665, 2018). "Many proteins associated with cancer, such as S100A9, MUC 1, NGAL, CEACAM6 and several other biomarkers have been identified in bile in patients with malignant biliary strictures, further suggesting the importance of bile in proteomic analysis." (PMID 25304323, 2015).